PDGFRA (platelet derived growth factor receptor alpha)
Diseases named in the same sentence as PDGFRA in open-access papers (continued):
Sharing a sentence is not in itself a finding about the gene and the disease.
glioma (continued). "Here we present deep profiling of whole proteome, phosphoproteome and transcriptome in two high-grade glioma (HGG) mouse models driven by mutated RTK oncogenes, PDGFRA and NTRK1, analyzing 13,860 proteins and 30,431 phosphosites by mass spectrometry." (PMID 31420543, 2019). "We initially focused on CTCF-bound insulators that demarcate a TAD boundary upstream of a known glioma oncogene, PDGFRA." (PMID 31534142, 2019). "Our new model offers a unique opportunity to study PDGFRα signaling in a context (glioma)-specific fashion." (PMID 30456354, 2018). "In conclusion, using comprehensive maps of molecular interactions and signaling events downstream of PDGF receptors, we revealed the context dependency of PDGFRα signaling output in a new model of glioma." (PMID 30456354, 2018). "We demonstrate the usefulness of this approach using a new genetically engineered mouse model of PDGFRα-driven glioma." (PMID 30456354, 2018). "An example of integrative DNA–RNA SV analysis is demonstrated in the detection of a complex PDGFRA gene fusion in a high-grade glioma." (PMID 30262806, 2018). "PDGFRA-associated gliomas were enriched in oligodendrogenesis genes, EGFR-low in the signature of mature neurons and PDGFRA-low in the signature of oligodendrocytes." (PMID 30279357, 2018). "This is indirectly supported by the alteration of PDGFRα signaling pathway in gliomas, the same pathway that is involved in normal development of oligodendrocytes by controlling proliferation and migration of OPCs." (PMID 30213051, 2018). "Targeted therapies against PDGFRA are in clinical trials for glioma and approved for metastatic GIST." (PMID 30389923, 2018). "To further improve PDGFR signaling networks in a clinically relevant context, we created a mouse model of glioma based on overexpression and constitutive activation of PDGFRα." (PMID 30456354, 2018). "Taken together, these results present a cross-mammalian set of neoplastic alterations in PDGFRA-overexpressing glioma, as well as unique contributions and possible limitations related to the tumor host species." (PMID 29352201, 2018). "Candidate genes should include oncogenic drivers ATRX and/or PDGFRA as they are present at significant frequency in lower grade gliomas." (PMID 29953513, 2018). "The human PDGFRA overexpressing glioma DEG dataset was then compared to the rodent and canine PDGFRA overexpressing glioma DEG datasets together." (PMID 29352201, 2018). "PDGFA/PDGFRα-regulated GOLM1 promotes glioma progression possibly through activation of a key signaling kinase, AKT." (PMID 29282077, 2017). "miR129-2 also suppresses the expression of platelet-derived growth factor receptor-alpha (PDGFR-α) in glioma cells." (PMID 28536635, 2017). "In vitro studies suggest Dasatinib as a good therapeutic option for PDGFRA amplified pediatric high-grade glioma." (PMID 29312620, 2017). "Many clinical trials evaluating the efficacy of anti-PDGFRA therapies on human gliomas are in development." (PMID 29282077, 2017). "Disruption of a topological domain boundary by DNA methylation upregulates the oncogene PDGFRA in IDH mutant gliomas." (PMID 28859663, 2017). "Focal amplifications of the locus at 4q12 harboring PDGFRA have been observed in almost all molecular subtypes of human glioma but more frequently in the proneural subtype." (PMID 29282077, 2017). "PDGFRA was also available to control the proliferation of glioma cells via the ERK-dependent mechanism." (PMID 28837560, 2017).
glioma (continued). "Here, we examined the role of GOLM1 in the development of human glioma and its functional relationship with PDGFRα." (PMID 29282077, 2017). "Functional assays in glioma cell lines confirmed this association and illuminated a potential role for GOLM1 in PDGFRα signaling." (PMID 29282077, 2017). "RAS/MAPK activation in glioma has been shown to result both from constitutive activation of receptor tyrosine kinases EGFR, PDGFRA, and c-MET as well by an inactivating mutation of NF1, a suppressor of RAS GTPase activity." (PMID 28256619, 2017). "Determining the relative contribution of EGFR/PDGFRA transactivation to glioma signaling is complicated by the prevalence and heterogeneity of expression of both receptors in gliomas." (PMID 28831081, 2017). "In IDH mutated gliomas, this mechanism leads to the close interaction of FIP1L1 gene and Platelet-Derived Growth Factor Receptor, Alpha Polypeptide (PDGFRA) gene, which are normally confined to separate loop domains." (PMID 27723796, 2016). "EGFR, PDGFRA, FGFR1, FGFR2, FGFR4 and MET are frequently amplified, mutated, or fused in high-grade gliomas or in secondary GBMs." (PMID 27385209, 2016). "This allows the constitutive enhancer FIP1L1 to interact aberrantly with PDGFRA, a prominent glioma oncogene." (PMID 27723796, 2016). "In‐frame deletions in PDGFRA's dimerization domain have also been observed in pediatric high grade gliomas, and those studies implicate constitutive receptor signaling too." (PMID 27888226, 2016). "Amplifications and mutations of PDGFRA, KIT and KDR were found in 8-15% of RMPAhigh gliomas, followed by EPHB3 (7.7%), FGFR1 (5.9%), FGFR3 (5.9%) and MET (4.1%)." (PMID 27385209, 2016). "This combined network linked both PRKG1 and CFTR to genes already known to be of importance in glioma biology such as PDGFRA, met, and TGFβ2, amongst others." (PMID 27564115, 2016). "We were unable to acquire additional HGG cell cultures with PDGFRA alterations, which limited our ability to confirm that the potency of dasatinib was generalizable to all glioma cells with PDGFRA up-regulation." (PMID 27582545, 2016). "When ectopically over‐expressed, in patient‐derived glioma cell lines, PDGFRAΔ7 enhances proliferation compared to wild‐type PDGFRA over‐expression." (PMID 27888226, 2016). "This network includes mRNAs from genes already known to be of importance in glioma biology, e.g., PDGFRA, met, and TGF-β2." (PMID 27564115, 2016). "PDGF signaling is known to be an initial driving event in glioma evolution, and high level focal amplification of PDGFRA is a feature of the proneural subtype of GBM." (PMID 27806344, 2016). "We have utilized two independent pediatric high-grade glioma cell lines with either high platelet-derived growth factor receptor alpha (PDGFRα) or high PDGFRβ expression in in vitro assays to investigate the specific downstream effects of nilotinib treatment." (PMID 25732621, 2015). "We have developed a new glioma mouse model based on cell-autonomous activation of PDGFRα in oligodendrocyte precursor cells (OPCs)." (PMID 25683249, 2015). "Enhanced effects were observed when regorafenib was combined with irradiation and irinotecan against PDGFRA amplified IGRG93 glioma and IGRM57 medulloblastoma respectively, resulting in 100% tumor regressions." (PMID 26599335, 2015). "NG2+ cells that often co-express PDGFRα and Olig-2 are present in adult gliomas, where NG2 contributes to the neoplastic transformation of glioma precursor cells." (PMID 25987129, 2015). "In further support, PDGFRA amplification is present in more than 15% of human grade III anaplastic astrocytoma and anaplastic oligodendroglioma, consistent with PDGFRA amplification as an early transforming event during glioma progression." (PMID 25683249, 2015). "We demonstrate that gB is endogenously expressed in primary GBM samples and show that ectopic gB expression in glioma cells induced sustained phosphorylation of PDGFRα, Akt, and Src." (PMID 24658280, 2014).
glioma (continued). "Confocal immunostaining analyses showed that about 10% of PDGFRA co-localized with caveolin-1, even though the protein is lowly expressed in glioma cells." (PMID 24489888, 2014). "Using newly established glioma cell lines isolated from 8 glioblastomas and 6 grade II astrocytomas, we have assessed glioma cell proliferation in the context of PDGFRA expression on cell surface." (PMID 24489888, 2014). "High levels of surface PDGFRA also correlated to high tubulin expression in glioma tumor tissue in vivo." (PMID 24489888, 2014). "Previous studies have shown that PDGFRA is overexpressed in 30% of human gliomas, and that enhanced PDGFRA expression is essential in mouse glioma models." (PMID 24489888, 2014). "To investigate the pathway involved in U0126-dependent reduction of surface PDGFRA expression on glioma cells, we focused on the ERK pathway since a series of studies reported that U0126 inhibits the phosphorylation of ERK by MEK." (PMID 24489888, 2014). "Intriguingly, U0126 treatment decreased the co-localization of PDGFRA and caveolin-1 from 10% to about 2%–3% in the glioma cell line #2." (PMID 24489888, 2014). "In this context the cell surface expression of PDGFRA is an important determinant of ligand sensing in the glioma microenvironment." (PMID 24489888, 2014). "Our findings suggest that the trafficking of PDGFRA in glioma cells is regulated by MEK and ERK activity and can potentially be manipulated to combat glioma growth." (PMID 24489888, 2014). "PDGF-AA has been previously shown to induce glioma cell invasion by activating PDGFRα in conjunction with recruitment of integrin αvβ3 to the focal adhesion cellular contacts a process dependent on activation of the Src oncogene." (PMID 24658280, 2014). "To observe the effects of cytoskeleton on surface PDGFRA expression in living glioma cells, we disrupted cytoskeletal organization by pharmacological inhibitors in the glioma cell lines #1, #2 and #3 with high surface PDGFRA expression." (PMID 24489888, 2014). "Treatment of PDGFRA expressing glioma cells with MEK inhibitor U0126 resulted in a transient decline of ERK phosphorylation, followed by up-regulated phosphorylation of ERK." (PMID 24489888, 2014). "Firstly, combined treatment with U0126 and VBT resulted in a synergistic effect in the reduction of cell surface expression of PDGFRA compared to U0126 treatment alone in the glioma cell lines #2, #3 and #5 with high surface PDGFRA expression." (PMID 24489888, 2014). "Aberrant phosphotyrosine-based signaling is a hallmark of cancer, and gliomas are no exception; tyrosine kinase membrane receptors like EGFR, ERBB2, PDGFRA, MET and VEGFR2 have been implicated in glioma growth, angiogenesis and cell motility." (PMID 25238264, 2014). "In glioma cell lines, surface PDGFRA declined following treatment with inhibitors of tubulin, actin and dynamin." (PMID 24489888, 2014). "U0126 dependent decline of surface PDGFRA expression was dose-dependent with significant effects evident within the range of 10 to 50 μM as shown in the glioma cell line #2 with high surface PDGFRA expression." (PMID 24489888, 2014). "Immunohistochemical staining in glioma tissues showed that gliomas with high surface PDGFRA expression presented higher expression of β-tubulin than gliomas with low surface PDGFRA expression." (PMID 24489888, 2014). "Our report extends on previous studies in that we demonstrate the importance of trafficking and surface expression of PDGFRA for glioma growth." (PMID 24489888, 2014). "In both cell lines and their corresponding tumor samples, glioma cell proliferation correlated with the extent of surface expression of PDGFRA." (PMID 24489888, 2014). "In another study, Cediranib, a potent inhibitor of VEGFRs, which also targets KIT and PDGFRA, was shown to induce a significant reduction of U251 glioma cells in S phase and a higher percentage of apoptotic cells." (PMID 24922514, 2014).
glioma (continued). "Taken together, our data supports an important role for HCMV gB signaling via PDGFRα to promote glioma pathogenesis." (PMID 24658280, 2014). "In particular, PDGFRα overexpression has been detected in all subtypes of gliomas, especially in glioblastoma." (PMID 24709958, 2014). "To address this point, we measured cell proliferation by BrdU incorporation in glioma cells with low or high surface expression of PDGFRA." (PMID 24489888, 2014). "PDGFRα and β are differently expressed in glioma, and in silico survival analysis revealed opposite effects and prognostic alternatives, unmasking the complexity of a therapeutic strategy targeting PDGFRs." (PMID 24023874, 2013). "Further, we performed immunohistochemical staining of FGF2 and PDGFRA expression in cohort of 6 low-grade and 17 high-grade glioma samples." (PMID 23630597, 2013). "Under the supervision of morphological diagnosis, analysis of the GSE16011 and the Repository of Molecular Brain Neoplasia Data (Rembrandt) set revealed enriched PDGFRA expression in low-grade gliomas." (PMID 23630597, 2013). "Compared to the uncultured cells analyzed simultaneously, cultured cells from all 3 glioma specimens showed enhanced levels of PDGFRA expression." (PMID 23630597, 2013). "To characterize the differential PDGFRA expression patterns in the various glioma subtypes, we compared PDGFRA expression among glioma morphological subtypes in GSE16011 and Rembrandt data sets including 244 and 404 gliomas of known diagnosis, respectively." (PMID 23630597, 2013). "Our findings indicated FGF2 signaling as a potential intervening target in glioma subset with enriched PDGFRA expression." (PMID 23630597, 2013). "In the Rembrandt data set, patients with PDGFRA-high GBMs or PDGFRA-high low-grade gliomas showed significant better survival and younger age at disease onset compared to patients with PDGFRA-low GBMs or PDGFRA-low low-grade gliomas, respectively." (PMID 23630597, 2013). "Further, concordant expression patterns of FGF2 and PDGFRA were detected in glioma samples by immunohistochemical staining." (PMID 23630597, 2013). "Our findings suggest a role of FGF2 in regulating PDGFRA expression in the subset of gliomas with younger age at disease onset and longer patient survival regardless of their morphological diagnosis." (PMID 23630597, 2013). "Further, the occurrence and clinical relevance of PDGFRA expression in different glioma subtypes is debated and controversial as both enhanced as well as negative expression patterns have been reported in GBM." (PMID 23630597, 2013). "In particular, autocrine stimulation of PDGFRA signaling is suggested to be important for glioma initiation and progression." (PMID 23630597, 2013). "FGF2-dependent PDGFRA expression appears to be a converged mechanism in normal glial development and glioma genesis." (PMID 23630597, 2013). "Inhibition of PDGFRA signaling resulted in a reversion of transformed phenotype in glioma cell lines, or a reversion from high-grade to lower grade tumor histology in mouse model." (PMID 23630597, 2013). "Patients with PDGFRA-high gliomas survived significantly longer compared to patients with PDGFRA-low gliomas (p = 0.028 and p = 0.001 in GSE16011 and Rembrandt, respectively, log-rank test)." (PMID 23630597, 2013). "Previous studies have also demonstrated crucial roles of PDGFRA signaling in gliomagenesis and shown that it is overexpressed in 30% of human gliomas." (PMID 23630597, 2013). "We analyzed the survival and clinical diagnoses in gliomas with the upper 25% PDGFRA expression levels (PDGFRA-high gliomas) and compared to gliomas with lower 25% levels of PDGFRA expression (PDGFRA-low gliomas)." (PMID 23630597, 2013). "In both data sets, the expression of PDGFRA was enriched in low-grade (grade II) gliomas compared to high-grade (grades III and IV) gliomas (p<0.001 and p = 0.002 in GSE16011 and Rembrandt, respectively, t test)." (PMID 23630597, 2013).
glioma (continued). "Signaling of platelet derived growth factor receptor alpha (PDGFRA) is critically involved in the development of gliomas." (PMID 23630597, 2013). "Using two large data sets consisting of 648 glioma samples of known morphological diagnosis, we found that under the supervision of morphological diagnosis, PDGFRA expression was enriched in low-grade gliomas compared to high-grade gliomas." (PMID 23630597, 2013). "Overexpression of PDGFRA is present in human low-grade gliomas and further enhanced by gene amplification in a subset of high-grade glioblastoma, whereas PDGF-B induces angiogenesis characteristic for secondary glioblastoma." (PMID 23998913, 2013). "These gliomas were significantly associated with frequent IDH1 mutation, younger age at disease onset and better survival outcome compared to the gliomas with lower levels of PDGFRA expression." (PMID 23630597, 2013). "It was recently shown that coexpression of phosphorylated Dock180 (Y1811), phosphorylated Src (Y418) and PDGFRα was predictive for extremely poor prognosis in patients with gliomas." (PMID 24358106, 2013). "The gene expression profile of group 1 DIPG was significantly enriched for the gene set describing the signature of PDGFRA amplified gliomas described in the TCGA and in children (GSEA analysis: enrichment score 0.59, FDRq = 0.038, p nominal = 0.052)." (PMID 22389665, 2012). "Our findings indicate that proneural gliomas are specifically characterized by miR-34a downregulation with subsequent derepression of the miRNA's downstream target PDGFRA, a process that promotes tumorigenesis both in vitro and in vivo." (PMID 22479456, 2012). "This consideration is particularly relevant to proneural gliomas, which, despite their strong associations with dysregulated PDGF signaling, only harbor mutations and or amplifications of PDGFRA in a minority of cases." (PMID 22479456, 2012). "We then show that miR-34a specifically inhibits growth in proneural glioma cells both in vitro and in vivo and identify PDGFRA as a direct and functionally consequential miR-34a target." (PMID 22479456, 2012). "Of these, three mice had gliomas that expressed PDGFRα and eGFP in high-grade tumor areas, concomitant with reduced proliferation rates (p<0.0001)." (PMID 21754979, 2011). "In adult mice, infusion of PDGF into the environment of NPCs that express PDGFRα can lead to early hyperpastic astrocytic lesions that have many characteristics of early stage gliomas." (PMID 22030012, 2011). "Both PDGFs and PDGFRs are upregulated in human gliomas andastrocytomas, and PDGFRα mRNA expression levels are higher in more advancedforms of gliomas than in less malignant glial tumors." (PMID 21559523, 2011). "These PDGF-induced experimental gliomas are similar to human GBs in that the glial tumor cells express Pdgfrα whereas the vasculature expresses Pdgfrβ in pericytes." (PMID 21209724, 2011). "PDGFA and PDGFRA expression was evaluated by immunohistochemistry in a series of 160 gliomas of distinct World Health Organization (WHO) malignancy grade." (PMID 19707201, 2009). "Given the retrospective nature of our study, further analysis of the prognostic impact of PDGFA and PDGFRA expression in gliomas is warranted." (PMID 19707201, 2009). "The concurrent expression of PDGFA and PDGFRA in different subtypes of gliomas, reinforce the recognised significance of this signalling pathway in gliomas." (PMID 19707201, 2009). "Since some gliomas express the PDGF-C receptors PDGFRα and PDGFRβ we checked for autocrine signaling in our U87MG cells." (PMID 19352490, 2009). "PDGFRA and PDGFA have been shown to be expressed in tumour cells, whereas PDGFB and PDGFRB have been found in glioma-associated endothelial cells." (PMID 19707201, 2009). "Analysis of PDGFRA gene copy number status as defined by QPCR was successfully performed in 57 gliomas." (PMID 19707201, 2009).